BCL2 (BCL2 apoptosis regulator)
Diseases named in the same sentence as BCL2 in open-access papers (continued):
Sharing a sentence is not in itself a finding about the gene and the disease.
cancer (continued). "Altogether, these data suggest that transcription termination defects interfere with the expression of neighbouring genes and illustrate a new paradigm for the aberrant expression of cancer-related genes, which may explain the upregulation of the BCL2 oncogene in ccRCC." (PMID 26575290, 2015). "It has been shown that oncogenes and/or tumour suppressor genes may be disrupted dramatically by modulating miRNAs in human cancers; for example, miR-16-1 and miR-15a negatively regulate BCL2 production and miR-17-92 cooperates with c-Myc to stimulate proliferation." (PMID 25297811, 2014). "Additionally, the death-associated protein kinase, DAPK, a protein that phosphorylates Beclin-1 thereby disrupting Beclin-1/BCL-2 complex and favoring autophagy, is another inducer of autophagy that is commonly silenced in different types of human cancers by methylation." (PMID 25328887, 2014). "Since this construct contains the three Bcl-2 homology (BH) sequence motifs which participate in forming a binding site for inhibitors of hMcl-1, it is deemed to be crucial for structure-based design of novel anti-cancer drugs blocking the Mcl1 related anti-apoptotic pathway." (PMID 24789074, 2014). "Therefore, simultaneous inhibition of the MEK-MAPK axis and BCL-2 could represent a way to effectively promote BIM-induced cancer cell apoptosis." (PMID 25621297, 2014). "Anti-apoptotic Bcl-2 family proteins, including Bcl-2, Bcl-XL, Bcl-w, Mcl-1 and A1, prevent cell death by binding and sequestering pro-apoptotic proteins so, inhibition of these anti-apoptotic proteins might be lethal to cancer cells." (PMID 24393539, 2014). "Therefore, depending on the cancer cell type and conditions, the regulation of some pro-/anti-death Bcl-2 proteins may be influenced by GCR blockers and oxidative/nitrosative stress." (PMID 24802641, 2014). "This study may provide novel insights into the Bcl-2-targeted cancer therapeutics." (PMID 24779770, 2014). "Targeting these factors either by using an ABCB1inhibitor (vardenafil), a novel agent that can circumvent DNA repair (N3-propargyl analogue of TMZ) or a BH3 mimetic to inhibit BCL2 anti-apoptotic proteins (obatoclax) could all be viable therapeutic routes in this malignant tumour in children." (PMID 24887326, 2014). "In conclusion, this meta-analysis indicates that Bcl-2 -938C>A polymorphism might be associated with increased cancer risk and this association might exist in Asians but not in Caucasians." (PMID 25430556, 2014). "Furthermore, Bcl-2 -938 C>A polymorphism was significantly associated with increased cancer risk in Asians but not in Caucasians." (PMID 25430556, 2014). "The expression of BCL2 in normal epithelium suggests that BCL2 may also be expressed in carcinoma." (PMID 26556430, 2014). "In some cancer cells, which are equipped with increased levels of pro-apoptotic proteins Bid and Bax, it might be possible to reduce cell-to-cell variability by inhibiting Bcl2-like anti-apoptotic proteins and altering the Bcl2 to Bax ratio." (PMID 24709706, 2013). "The combination of staurosporine and ABT-737 at any concentration, i.e. for any decrease in Bcl2 total protein amount, was predicted by the model to induce much more apoptosis in parental cells compared to Src-transformed cells and thus to fail in circumventing cancer cells resistance." (PMID 23592961, 2013).
cancer (continued). "Thus, due to the intimate interplay between BCL2-like family members and bioactive sphingolipids in apoptotic regulation, drugs that target both ceramide metabolism and anti-apoptotic BCL2 proteins may be good candidates for synergistic cancer therapies." (PMID 23342165, 2013). "For example, miR-34a represses the production of Bcl-2 and SirT1, two proteins displaying high levels of expression in cancer cells and implicated in promoting proliferation and cell survival, although miR-34a does not affect Bcl-2 expression levels in all cell systems." (PMID 23325049, 2013). "The anti-apoptotic Bcl-2 may regulate the mitochondrial redox state in cancer cells." (PMID 23431463, 2013). "This raises the question whether cancer cells, in particular Bcl-2-dependent malignancies, displayed altered Ca2+-signaling properties that turned these cells into vulnerable targets toward peptides disrupting Bcl-2-mediated suppression of apoptotic IP3R activity." (PMID 23681227, 2013). "This may explain why the prognostic implication of Bcl-2 expression depends on cancer type." (PMID 24088574, 2013). "Taken together, the Bax/Bcl-2 ratio of cancer cell might increase after malignant change." (PMID 24454344, 2013). "However, in cancer cells for which the Bcl2 to Bax ratio has reached a very high level, alternative strategies such as switching the activation from type 2 to type 1 may provide an option." (PMID 24709706, 2013). "It has been postulated that BCL2 expression may be suppressed during cancer progression." (PMID 23637776, 2013). "Therefore, it may be less critical for cancer cells to use Bcl-2 for suppressing the activity of IP3R3, because this isoform is the least sensitive to IP3 and thus to ongoing B-cell receptor (BCR) signaling." (PMID 23681227, 2013). "Furthermore, cancer cells themselves may also secrete factors such as IL-10 that lower DC survival by suppressing the anti-apoptotic genes Bcl-2, Bcl-XL, and Bfl-1." (PMID 23870437, 2013). "However cancer cells expressing miR-15b and miR-16 demonstrated a down-regulated Bcl-2." (PMID 23773282, 2013). "However, scoparone exerted no cytotoxic effects on the cancer cell lines we tested, even at the very high concentration of 1 mmol/L, although it caused downregulation of the anti-apoptotic proteins Bcl-2 and Survivin." (PMID 24260381, 2013). "However, regulation of ROS levels by Bc-2 was also demonstrated as Bcl-2 may affect the intracellular redox status in order to maintain the ROS potential at the most favorable level for cancer cell survival." (PMID 23762063, 2013). "Rapid detection of a primed for death state in individual cancers by “bioenergetics-based profiling” may eventually help identify the subset of patients with chemoresistant but primed tumors who can benefit from treatment that incorporates a BCL-2 antagonist." (PMID 22880001, 2012). "In addition, Bcl-2, an antiapoptotic member of the family and a resident protein of mitochondria, is able to modulate redox status which could be utilized in cancer therapeutics as well." (PMID 22593827, 2012). "Seeing that increased iNOS production and Bcl-2 expression have been associated with several human tumors, this finding on the novel function of MDA-7/IL-24 on regulation of Bcl-2 denitrosylation may provide a valuable mechanism for MDA-7/IL-24 induced cancer-specific apoptosis." (PMID 22629368, 2012). "In addition, the natural BH3 mimetic (−)-gossypol has been shown to kill cancer cells via autophagic cell death in Bcl-2-proteins-overexpressing, apoptosis-resistant cancer cells, strongly suggesting BH3 mimetics’ anti-tumor effects are not solely dependent on apoptosis." (PMID 24710477, 2012). "However, Bcl-2 is in addition the target of spontaneous T-cell reactivity in cancer patients." (PMID 21304176, 2010).
cancer (continued). "Hence, this method based on MOMP (mitochondrial outer membrane permeabilization) is an interesting screening tool, tailored for identifying Bcl-2 antagonists with selective toxicity profile against cancer cell mitochondria but devoid of toxicity against healthy mitochondria." (PMID 20360986, 2010). "Consequently, based on in vitro and in vivo findings in B16M cells (on the interaction between endothelial and metastatic cells, and the effect of ROS and RNS), GSH and Bcl-2 appear candidates to challenge survival of cancer cells with high metastatic potential." (PMID 24281071, 2010). "Thus, the blockage of Bcl-2 protein expression by HNTMB treatment could be useful to sensitize cancer cells to conventional therapies." (PMID 20184758, 2010). "Furthermore, the compression-induced apoptosis occurs via the mitochondrial pathway, a regulatory control mechanism that cancer cells with elevated Bcl-2 activity might escape to produce more malignant tumors." (PMID 19247489, 2009). "We performed a shRNA mediated knockdown of Msi1 in Daoy and found that cancer cells expressing low levels of Msi1 were less clonogenic (proliferation assay), more differentiated (higher βIII Tubulin expression) and, possibly, more apoptotic (lower Bcl2 expression)." (PMID 18826648, 2008). "Our findings suggest that, while the apoptosis inhibitor Bcl-2 might be a useful marker of HGPIN that is spatially associated with cancer, it does not however, appear to be a useful marker of high-risk normal tissue." (PMID 16545117, 2006). "In terms of relevance to cancer biology, the results have significance: they suggest that malignant breast cells are more resistant than nonmalignant cells to apoptotic induction, although possible differences in bcl-2 gene expression or other targets of SSP would also have an influence." (PMID 12556971, 2003). "Therefore, our data indicate that Bcl-2 is dispensable in the progression towards carcinoma." (PMID 9667656, 1998). "We then treated animals with the BCL-2/BCL-w/BCL-XL inhibitor ABT-263 at doses we and others have shown to be effective in cancer models." (PMID 41507122, 2026). "Overall, this review highlights the multifaceted contributions of BCL-2 and BCL-xL to cancer biology and underscores the importance of continued efforts to refine targeted therapeutic approaches." (PMID 41596764, 2026). "In recent years, BH3 mimetics such as ABT-263 and ABT-737, which inhibit activity of pro-survival proteins BCL-2, BCL-XL and BCL-W, have proven to be highly effective at eliminating cancer cells by directly inducing apoptosis." (PMID 41507122, 2026). "It was found that apoptosis was induced in cancer cells by increasing BAX levels and decreasing Bcl‐2 levels; CYCS and CASP3 levels, which are ROS‐assisted apoptotic markers, also increased." (PMID 40318008, 2025). "The PI3K/AKT signaling pathway contributes to chemoresistance in cancer by promoting antiapoptopic proteins such as BCL-XL and BCL-2, while inhibiting proapoptotic such as BAX." (PMID 40678416, 2025). "It is well established that Bcl-XL, Bcl-2, and MCL-1 are aberrantly expressed in many cancer cell lines, enabling these cells to circumvent apoptosis." (PMID 40400713, 2025). "miR-34a-5p targets many signaling molecules such as BCL2, CCND1, and SIRT1 that have a key role in the biological activities of cancer cells." (PMID 40061926, 2025).
cancer (continued). "Key molecules for cancer progression were inhibited (IL6, IL4, CXCL8, CXCR4, CXCL12; ICAM1, CD44 and BCL2), and pro-apoptotic BAD was activated." (PMID 41595551, 2025). "Several of the identified miRNAs directly targeted cancer-relevant genes such as PTEN, VEGFA, and BCL2, and five of them overlapped with the validated set, strengthening their consistency across analyses." (PMID 41226027, 2025). "This study suggests that the combination of BCL2 inhibitors and CDK4/6 inhibitors is a promising double-hit anti-cancer strategy." (PMID 40563591, 2025). "In summary, the interplay between ARTS, XIAP, and Bcl-2 in the UPS highlights an important regulatory axis in apoptosis, with the potential to be exploited in cancer therapy." (PMID 40841912, 2025). "Navitoclax (ABT-263), a potent inhibitor of BCL-2, BCL-XL, and BCL-W, has demonstrated efficacy in eliminating a broad range of senescent cells, including therapy-induced senescent cancer cells." (PMID 40703657, 2025). "In a large-scale RNAi screening aimed at understanding cancer dependencies and synthetic lethal relationships, the top correlates of WSB2 co-essentiality were found to be MCL-1, BCL-2, and MARCH5, while the most strongly anti-correlated gene with WSB2 was BAX." (PMID 40699886, 2025). "Exosomes can convey biomarkers of cancer metastasis inhibition, such as miR-140-3p (which upregulate the expression of BCL9 and BCL2) and circFNDC3B (which inhibit miR-937-5p and upregulate TIMP3) in colorectal cancer." (PMID 41502528, 2025). "This pathway enhances the expression of anti-apoptotic proteins, such as BCL-2 and MCL-1, and inhibits pro-apoptotic signals, providing a survival advantage to cancer cells in the face of chemotherapeutic stress." (PMID 40149289, 2025). "First, there is a lack of robust, prospective data evaluating the long-term effectiveness of cancer screening, vaccinations, and IVIG replacement in patients with CLL and also in patients with CLL receiving targeted therapies such as BTK or BCL-2 inhibitors." (PMID 40647394, 2025). "For example, venetoclax (ABT‐199) precisely disrupts the interaction between B‐cell lymphoma 2 (BCL‐2) and BCL‐2‐like protein 11 (BIM), thereby inducing apoptosis in cancer cells." (PMID 40692663, 2025). "This review specifically focuses on resistance to BCL2 and MCL1 inhibitors, given their clinical relevance in cancer therapy." (PMID 41155156, 2025). "Apoptosis-mediated death of cancer cells is achieved by the upregulation of pro-apoptotic genes, such as BAX, BID, and BAK, and the downregulation of anti-apoptotic genes, such as BCL-2 and BCL-XL respectively." (PMID 40756996, 2025). "The AKT1 and Bcl-2 proteins are overexpressed in OSCC tissues and can promote cancer cell survival and proliferation." (PMID 41020907, 2025). "Together, these results demonstrate the consistent and effective knockdown of BCL-2 mRNA by DNZ-15 and DNZ-35a across multiple biologically relevant cancer cell lines, including human and murine models." (PMID 40643466, 2025).
cancer (continued). "Clinical trials evaluating the combination of BTK or BCL-2 inhibitors with ROR1-targeting therapies have yielded encouraging results, further underscoring the critical role of ROR1 in cancer progression and therapy resistance." (PMID 41479906, 2025). "Molecular docking studies confirmed stable binding interactions (binding energies: –4.9 to –6.8 kcal/mol) of BITC and CA with key cancer-related proteins (ERK2, p38 MAPK, Bcl-2, Keap1-Nrf2, GST)." (PMID 40799801, 2025). "Many studies have shown that STAT3 induces the transcription of genes involved in cancer cell proliferation and survival, such as CCND1, BCL2, and MYC." (PMID 41104968, 2025). "The apoptosis assay displayed the role of compound 24 in reducing the levels of BCL-2 and MCL-1, which led to apoptosis of the cancer cells." (PMID 40283934, 2025). "By elevating Bax and Caspase 3 levels and concurrently downregulating the anti-apoptotic protein BCL-2, HSP demonstrated an inhibitory effect on human cancer cell HT-29 through the induction of mitochondrial-mediated apoptosis." (PMID 40427522, 2025). "These DNAzymes downregulated BCL-2 expression, induced apoptosis, and reduced cell viability in HepG2 and MCF-7 cancer cells." (PMID 40643466, 2025). "Effect of CFSB, at its IC50 concentration, on the expression levels of Bax, Bcl2, caspases-3 and MMP9 in HepG2 cancer cells." (PMID 40396612, 2025). "BCL2 antiapoptotic proteins (BCL2, MCL1 and BCLxl) are currently considered as therapeutic targets in many types of cancer, due to their overexpression and the ability to apoptosis evasion." (PMID 39836700, 2025). "Resveratrol, another polyphenol found in grapes and berries, is known for its capacity to inhibit cancer progression by disrupting NF-κB-mediated transcription of inflammatory and anti-apoptotic genes, including COX-2, Bcl-2, and MMP-9." (PMID 40869364, 2025). "In summary, our data indicated that CSNK1D promoted HNSCC cancer progression by increasing the nucleus entry of GLI1 and activating the hedgehog GLI1/BCL2 signaling pathway." (PMID 41353440, 2025). "In cancer cells, NRF2 activation often leads to increased expression of anti-apoptotic proteins such as B-cell lymphoma 2 (Bcl-2) and Bcl-2-like protein 1 (Bcl-xL), which contributes to enhanced cell survival and drug resistance." (PMID 40746900, 2025). "Given the changes in BCL2, we also evaluated the effect of CQ on WT and PAK4 KO cancer cell apoptosis." (PMID 39941877, 2025). "BCL2 is a member of the BH3 family gene and is a well‐known anti‐apoptotic gene upregulated in many cancers." (PMID 40124717, 2025). "Previous studies have shown that inhibition of BCL-2 and CDK4/6 combined with endocrine therapy can inhibit proliferation and induce apoptosis of cancer cells, including phenotype senescent cells, thereby enhancing reactivity in vivo." (PMID 40104496, 2025). "NF-κB also promotes cancer cell survival under hypoxic conditions by stimulating hypoxia-inducible factor 1α (HIF-1α) and inducing anti-apoptotic genes such as Bcl-2, Bcl-xL, and inhibitors of apoptosis (IAP)." (PMID 40420174, 2025). "Induces apoptosis by upregulating Bax and downregulating Bcl-2, inhibits PI3K/AKT signaling, suppresses cancer cell proliferation, and enhances radiosensitivity." (PMID 40918117, 2025).